TPTEP1 (TPTE pseudogene 1 )
Synonyms: psiTPTE22
Gene: Long non-coding RNA gene on chromosome 22 (16,601,307 to 16,698,742, forward strand). Ensembl gene ENSG00000290418.
Diseases named in the same sentence as TPTEP1 in open-access papers:
TPTEP1 is named in the same sentence as 21 diseases in open-access papers, as found by Europe PMC text mining. Sharing a sentence is not in itself a finding about the gene and the disease. The quoted sentences say what the papers report.
glioma (7 papers, 2021 to 2026). A benign or malignant brain and spinal cord tumor that arises from glial cells (astrocytes, oligodendrocytes, ependymal cells). "Both in vitro and in vivo tumor xenograft studies confirmed that TPTEP1 knockdown enhanced glioma cell stemness and radioresistance-associated gene expression, such as OCT4, aldehyde dehydrogenase 1 (ALDH1), and γ-H2AX (the γ phosphorylated form of the histone H2AX)." (PMID 41431719, 2026). "lncRNA transmembrane phosphatase with tensin homology pseudogene 1 (TPTEP1) has been demonstrated to act as a tumor suppressor in glioma cells, and the upregulation of TPTEP1 in glioma patients has shown an improvement in overall survival probability." (PMID 34202078, 2021). "TPTEP1 attenuates miR-106a-5p, and the depletion of miR-106a-5p leads to cell stemness and radioresistance in glioma cells." (PMID 34202078, 2021). "While in glioma, lncRNA TPTEP1 downregulated radioresistance through miR-106a-5p/P38 MAPK." (PMID 35600868, 2022). "However, some elevated expression of LINC00312 in NPC, TPTEP1 in glioma, and NKILA in laryngeal carcinoma was found to be related to radiosensitivity." (PMID 36323697, 2022). "Distinctively dysregulated lncRNAs in gliomas include LOC150622 and LINC00645 in glioblastoma, LOC100216479 in diffuse H3K27M glioma, FLJ41350 and FTX in medulloblastoma, TPTEP1 and LOC100144595 in astrocytoma, and LOC100216545, FAM66B, and LOC100499405 in oligodendroglioma." (PMID 37693314, 2023).
hepatocellular carcinoma (5 papers, 2020 to 2024). A malignant tumor that arises from hepatocytes. "According to previous studies, the lncRNA TPTEP1 can interact with miRNAs or proteins to participate in cell proliferation and migration in many cancers, such as hepatocellular cancer and non‐small cell lung cancer." (PMID 39422584, 2024). "TPTEP1 expression was shown to inhibit hepatocellular carcinoma progression and non-small cell lung cancer proliferation." (PMID 35205253, 2022). "Our recent study reported that long non-coding RNA TPTEP1 inhibits hepatocellular carcinoma progression by interacting and suppressing STAT3 phosphorylation." (PMID 32123532, 2020). "Transmembrane phosphatase with tensin homology pseudogene 1 (TPTEP1) is a novel lncRNA that has been previously unveiled to repress tumor progression in hepatocellular carcinoma by hindering Signal transducer and activator of transcription 3 (STAT3) phosphorylation." (PMID 33985519, 2021). "TPTEP1 is a lncRNA that has been previously recognized as a tumor suppressor in hepatocellular carcinoma, while miR-1303 has been revealed to be upregulated and accelerate tumor development in several human cancers, such as hepatocellular carcinoma, neuroblastoma and gastric cancer." (PMID 33985519, 2021). "Among these, TPTEP1 was reported to suppress diabetic retinopathy by reducing oxidative stress, inhibiting stemness and radio resistance, and it exhibited substantial antitumor effects in several cancers, including hepatocellular carcinoma (HCC) and non-small-cell lung cancer (NSCLC)." (PMID 38279317, 2024). "Previous studies have shown that the expression of the lncRNA TPTE pseudogene 1 (TPTEP1) is widely suppressed in various cancers and that TPTEP1 can inhibit the proliferation, invasion and migration of hepatocellular cancer and non‐small cell lung cancer cells." (PMID 39422584, 2024).
fibroids (2 papers, 2024 to 2025). "In contrast to the findings in malignant tumors, leiomyomas which are benign expressed higher levels of TPTEP1 and CA3-AS1." (PMID 38279317, 2024).
gastric cancer (2 papers, 2021 to 2025). A primary or metastatic malignant neoplasm involving the stomach. "Functionally, the TPTEP1/miR-548d-3p/KLF9/PER1 axis reduces gastric cancer cell migration and invasion, with KLF9 serving as the critical regulatory node that translates the long non-coding RNA TPTEP1’s tumor-suppressive effects into PER1-mediated anti-metastatic activity." (PMID 40860800, 2025).
liver cancer (1 paper, 2021). An epithelial or non-epithelial malignant neoplasm that arises from the liver. "Further analyses found that TPTEP1 inhibits IL-6-induced phosphorylation of STAT3, thereby inhibiting the transcriptional activity of STAT3 and increasing the sensitivity of liver cancer cells to cisplatin." (PMID 33390845, 2021).
ovarian carcinoma (1 paper, 2024). A malignant neoplasm originating from the surface ovarian epithelium. "The expression of the long noncoding RNA (lncRNA) TPTE pseudogene 1 (TPTEP1) is significantly downregulated in ovarian cancer (OC)." (PMID 39422584, 2024). "In this study, RT–qPCR, Western blotting, RNA pull‐down, mass spectrometry and RNA immunoprecipitation were used to explore the function and mechanism of the long noncoding RNA (long noncoding RNA) TPTEP1 in OC to identify a new therapeutic target for ovarian cancer (OC)." (PMID 39422584, 2024). "In conclusion, our study confirms the important role of TPTEP1 in ovarian cancer (OC) progression and suggests that TPTEP1 inhibits the PI3K/AKT signalling pathway by directly binding PTBP1, possibly indicating the molecular mechanism underlying its biological function." (PMID 39422584, 2024).
tumor (12 papers, 2020 to 2026). "Our findings demonstrated increased expression levels of DDIT4 and TPTEP1 in CRC were associated with more aggressive tumor behavior and more advanced stages of the disease." (PMID 34107956, 2021). "In this study, we uncovered for the first time that TPTEP1 was an anti-tumor lncRNA and that miR-1303 was a facilitator in AML." (PMID 33985519, 2021). "Furthermore, the results of EdU, colony formation, wound healing, Transwell, flow cytometry, tumour formation assays in nude mouse, as well as WB analysis, showed that the lncRNA TPTEP1 can inhibit the proliferation, invasion and migration and promote the apoptosis of OC cells." (PMID 39422584, 2024). "TPTEP1 suppresses the progression of HCC cells by affecting the IL-6/STAT3 signaling pathway, revealing its tumor-suppressive role in HCC chemotherapy." (PMID 40352941, 2025). "Predictions based on the ENSG00000203739/ENSG00000271646-miR-637-CYBRD1 and TPTEP1-miR-196a-5p-RUFY2 regulation axes indicated that the two proteins may act as an oncogene and tumor suppressor, respectively, in the development of GBM." (PMID 32211330, 2020). "We identified some mutation markers specific to tumor types, including some typical tumor‐related genes (e.g., TP63, ABCC1, ABCC5, and TFDP1 in ESCA) as well as numerous noncoding genes (e.g., NPSR1‐AS1 and AC079466.1 in HCC) and pseudogenes (e.g., SDHAP3 and TPTEP1 in LUAD)." (PMID 38010945, 2024). "As patients with G-CIMP subtype tumors in general have a better prognosis, low-expression of TPTEP1 in non-G-CIMP subtypes may be consistent with a role as a tumor suppressor gene." (PMID 32211330, 2020). "Based on the theory of ceRNA, we found potential ncRNA regulatory pathways involving an oncogene and a tumor suppressor, ENSG00000203739/ENSG00000271646-miR-637-CYBRD1 and TPTEP1-miR-196a-5p-RUFY2, and constructed a local PPI network which might contribute to proliferation and invasion of GBM." (PMID 32211330, 2020). "Overexpression of DDIT4 and TPTEP1 in CRC patients with metastasis and advanced stages as well as in colorectal CSC-enriched spheroids indicates that increased RNA expression of these markers may be useful indicators of more aggressive tumor behavior and further disease progression in CRC patients." (PMID 34107956, 2021).
cancer (6 papers, 2020 to 2024). A tumor composed of atypical neoplastic, often pleomorphic cells that invade other tissues. "Contrary to the lung and liver cancer studies, the expression of TPTEP1 showed an up-regulation pattern in our CRC tissues compared to the adjacent normal tissues." (PMID 34107956, 2021). "Moreover, we observed higher expression of TPTEP1 in colorectal CSC-enriched spheroids than HT-29 cancer cells." (PMID 34107956, 2021). "After detection of CSC features, the RNA expression levels of DDIT4, SULF1, TPTEP1 and miRNAs (miR-181d-5p and miR-148b-3p) were measured using RT‐qPCR in colorectal CSC-enriched spheroids and HT-29 cancer cells." (PMID 34107956, 2021). "The official symbol of ENSG00000100181 is TPTEP1, which is also known as psiTPTE22. psiTPTE22-HERV has been reported to be epigenetically silenced by DNA methylation in cancers of the kidney, liver, lung, and stomach." (PMID 32211330, 2020). "Moreover, we unveiled that TPTEP1 confined AML cell proliferation through inactivating JNK/c-JUN signaling, a well-known oncogenic pathway verified in a variety of cancers, including AML." (PMID 33985519, 2021). "We also highlight the prognostic value of HPN-AS1, TPTEP1, and LINC00623 in cancer outcomes." (PMID 33082888, 2020).
TPTEP1 also shares sentences with these, for which no sentence is quoted: non-small cell lung carcinoma (3 papers); acute myeloid leukemia (1); astrocytoma (1); colorectal cancer (1); diabetic retinopathy (1); glioblastoma (1); laryngeal carcinoma (1); lymph node metastasis (1); medulloblastoma (1); neuroblastoma (1); oligodendroglioma (1); osteosarcoma (1); pancreatic tumor (1).